CD24 (CD24 molecule)
Diseases named in the same sentence as CD24 in open-access papers (continued):
Sharing a sentence is not in itself a finding about the gene and the disease.
cancer (continued). "More importantly, they were resistant to cisplatin, oxaliplatin and cyclophosphamide exhibiting high cross-resistance along with alterations in expression of cancer-stem cell markers such as CD133, CD166, CD24, CD26, CXCR4, CD271 and CD274." (PMID 30143021, 2018). "CD24 is a glycosylphosphatidylinositol (GPI)-anchored cell surface protein with a broad expression in hematopoietic cells and cancer cells." (PMID 29423273, 2018). "Cancer stem cells (CSCs), which have roles in survival andchemoresistance, are commonly analyzed according to theexpression of CD44 and CD24 markers." (PMID 29845783, 2018). "BCCs from cell lines and blood from BC patients were analysed for these three membrane proteins by flow cytometry, along with known markers of cancer stem cells (CSCs), CD44, CD24 and Oct4, aldehyde dehydrogenase 1 (ALDH1) activity and telomere length." (PMID 29321622, 2018). "In this study, the combination panel (CD24, CD49f, and NANOG) yielded high sensitivity for cancer detection not only for NMIBC (80.9%), but also for low-grade UCB (80.0%)." (PMID 30327565, 2018). "We also found leptin to increase the stemness of both cancer cell lines, as indicated by aldefluor activity, CD44/CD24 expression, and mammosphere formation." (PMID 28542577, 2017). "Multiplex transcriptome profiling of single CTCs revealed presence of sub-populations of CTCs expressing multiple pro-cancer transcripts including cancer stem cell markers such as CD44 and CD24." (PMID 28626429, 2017). "In such a case, we can also develop additional OAds targeting CSCs by focusing other cancer stem cell markers, such a CD44 or CD24." (PMID 29100290, 2017). "The same phenomenon was also observed in liver (CD24+ and CD133+) and colon (CD44+ and CD26+) cancers." (PMID 28633632, 2017). "To further understand the mechanism of CD24-regulated drug sensitivity in TNBC, we also assessed other cancer stem cell markers, such as ALDH, CD133 and CD49f." (PMID 28418843, 2017). "To further validate our findings, we used a second independent approach to quantitate “stemness” in cancer cells, by employing specific cell surface markers, namely fluorescent antibody probes directed against CD44 and CD24." (PMID 29253841, 2017). "We observed overexpressed EXT1 in MCF7/ADR cells can facilitate and regulate cancer cell stemness, including increased ALDH+and CD44+/CD24- population, and growth of larger and more numerous mammospheres in MCF7/ADR cells." (PMID 29050299, 2017). "Patient-derived aspirates were cultured under sphere forming conditions and isolated primary cultures were further sorted for cancer stem cell subpopulations ALDH1+ and CD44+CD24-/low." (PMID 28423035, 2017). "siRNA-mediated knockdown of EXT1 in MCF7/ADR cells significantly reduced cancer stem cell markers, populations of ALDH+and CD44+/CD24- cells, mRNA and protein expression for CD44, and mammosphere number." (PMID 29050299, 2017). "Overexpression of syndecan-1, MUC-1, and the putative cancer stem cell markers CD15, CD24, CD44, and CD133 has been documented on CSF floating cancer cells of BC patients with LM." (PMID 28399903, 2017). "A minority of cancer cell population, called cancer stem cells (CSC), with CD44(+/high)CD24(−/low) signature, has been identified in a large variety of cancers." (PMID 28165047, 2017). "There are a variety of cell surface markers used to identify and enrich CSCs from different human cancers, such as CD44, CD24, CD29, CD133 and epithelial cell adhesion molecule (EpCAM)." (PMID 28969077, 2017). "UCAPe cells differed from the mesenchymal cells by the surface expression of PD-L1, E-cadherin, CD24, and VEGFR2 and exhibited the hallmarks of cancer stem cells, immune evasion, transformation, and in particular, rapid tumorigenesis." (PMID 28851898, 2017). "The distribution of CD24 protein was predominantly membranous in OE19 cells, while membranous and cytoplasmic staining were observed in the OE33 cancer cell line." (PMID 28611669, 2017).
cancer (continued). "Results of this experiment demonstrated decrease in CD24 and CD44 expressions in carcinomas, on the other hand increase in ALDH1 after treatment with CLOs." (PMID 28524540, 2017). "Analysis of carcinoma cells in animals showed bcl‐2, Ki67, VEGFA, CD24 and CD44 expression decrease and Bax, caspase‐3 and ALDH1 expression increase after high‐dose CLO administration." (PMID 28524540, 2017). "It is important to study CD24 and CD133 markers, due to their relationship with metastasis and recurrence, as well as their resistance to anti-cancer treatments like chemotherapy." (PMID 27099673, 2016). "In pancreatic cancer, combination of two distinct expression patterns, such as of CD44/CD24 together with the epithelial-specific antigen (ESA) or CD133/CXCR4, can identify the cancer stem-like population." (PMID 27457474, 2016). "This way, we found 102 genes differentially expressed in CD24+ cancer cells compared to CD24+ normal breast epithelium cells, and 63 genes differentially expressed in CD44+ cancer cells compared to CD44+ normal breast epithelium cells." (PMID 26673618, 2016). "Enriched SFCs in serum-free suspension culture exhibited cancer stem-like cell properties and increased single-positive CD44 + CD24-, stemness factor, mesenchymal marker expression ABC transporters and tumorigenicity in vivo compared with the parental cells." (PMID 27189061, 2016). "Genome-wide gene expression profiling of these two models identified CD24, a known CSC marker in various types of human cancers, as a differentially expressed gene." (PMID 27659530, 2016). "Several reports suggest that CD24, CD44s including CD44v6, and ALDH1A1 are putative markers for cancer stem cells." (PMID 27647953, 2016). "Cell phenotype was evaluated following staining and flow cytometry analysis for the following surface antigens; cancer stem cell markers, CD44 and CD24." (PMID 27632425, 2016). "Previous studies revealed that CD24 mediated gastric carcinogenesis and promoted cancer cell progression via STAT3 activity, and regarded various CD24-mediated genes as STAT3 target genes." (PMID 27494878, 2016). "Here, we used cell lines and xenograft models recently generated in our laboratory to screen for cancer stem cells using several combinations of ALDH, CD44, CD24, and CD10 markers." (PMID 26449187, 2015). "When the MDA-MB-231 cancer cell media was changed from MEM to DMEM for 48 h, expression levels of CDH1 and CD24 were significantly reduced." (PMID 25776572, 2015). "To begin to understand the ability of marker combinations to select for cancer stem cells, we FACS-sorted the UM-HMC-3A and UM-HMC-3B cell lines according to ALDH activity, CD10, CD24, and/or CD44 protein expression." (PMID 26449187, 2015). "In order to further determine the effects of SATB1 expression on the cancer stem cell population, the effects of SATB1 overexpression in MCF-7 cells and SATB1 knockdown in BT-549 cells on CD44+/CD24− populations were investigated." (PMID 25586771, 2015). "Consistent with published reports we found low- and high-expressing cancer cells with regard to ALDH1 and CD24; concerning CD117 and CD133 only antigen-positive and -negative cancer cells were observed." (PMID 25999351, 2015). "The CD24+CD44+ESA+ cells, which was also documented to be with characteristics of cancer stem cells, didn’t show high capacity to resist gemcitabine." (PMID 26391180, 2015). "CD24 (cluster of differentiation 24) and ESA (epithelium specific antigen) were also used as special markers of cancer stem cells." (PMID 24689055, 2014). "Thus, targeting CD24 may offer new approach for therapy of human cancer including HNSCC." (PMID 24612587, 2014). "Analysis of cell surface antigens showed strong expression of cancer stem cell antigens CD44 and epithelial-specific antigen (ESA) in SKBR3 mammospheres, whereas expression of CD24, epithelial cell marker was low." (PMID 23341935, 2013).
cancer (continued). "Therefore, CD24 inhibition may be considered as an effective approach for cancer therapy." (PMID 23509802, 2013). "We have recently found that P-cadherin enriched cell populations show enhanced mammosphere forming efficiency (MFE), as well as increased expression of CD24, CD44 and CD49f, already described as normal or cancer stem cell markers." (PMID 23405208, 2013). "The patients with the features of both MBC and basal-like cancers had enrichment for stem cell-like markers with an elevation of CD29/CD24 and CD44/CD24 ratios." (PMID 23738706, 2013). "Here, to study the effects of CK2α on cancer stem cell maintenance via regulating Notch1, we first examined CD44 and CD24 expression after treatment with 50 μM CK2α siRNA." (PMID 23651443, 2013). "The cancer stem cells with triple positive makers, (CD44+CD24+ESA+ cells) comprised only 1.0% of the cells in monolayers, but this value showed a statistically significant increase to 2.9% in spheroids." (PMID 24039920, 2013). "Cells with a CD44+/CD24- phenotype were detected in 40 out of 130 samples with an advantage of high grade tumors (II and III) and metastases among tubular, papillary and carcinomas in mixed tumors." (PMID 24119896, 2013). "Flow cytometry was used to study the co-expression of EpCAM with putative cancer stem cell markers, such as CD44, CD24, and ABCG2, in RB primary tumors." (PMID 22328825, 2012). "Owing to current contradictions, we herein review recent literature and discuss the importance of CD44 and CD24, as potential surface markers in identification and isolation of CSC, in different cancers." (PMID 22693526, 2012). "Using flow cytometry, we studied the individual expression of EpCAM, CD44, CD24 and ABCG2 and also studied the co-expression of EpCAM with other three putative cancer stem cell markers." (PMID 22328825, 2012). "To investigate the efficiency of ARR in inhibiting the growth of cancer stem cells, we examined the inhibition of sphere formation in CD44+/CD24+/EpCAM+ and CD133+ cancer stem cells." (PMID 22570653, 2012). "CD24, CD73, CD117 and integrin α2β1 expressions were higher in the mesenchymal-like cells deriving from ascites or cancer tissues than the normal HOTC, but lower in epithelial-like cells from ascites." (PMID 22330345, 2012). "Recent investigations found that CD24 is coexisting with CD44, CD29, and CD31 in various cancers and gained new interest as a CSC marker." (PMID 22693526, 2012). "Recently a small subset of cancer cells was identified by their cell surface markers (e.g., up-regulation of CD44 and down-regulation of CD24) as cancer stem cells (CSCs)." (PMID 23226410, 2012). "We investigated the expression of four markers that have previously been described for isolation of several types of human CSCs in human cancer cell lines: CD44, CD24, ABCG2, and EpCAM." (PMID 22328825, 2012). "EpCAM was co-expressed with all cancer stem cell markers (CD44, CD24, and ABCG2) in primary RB tumors." (PMID 22328825, 2012). "We also discuss CSCs differential proportionalities in various cancer cell lines and mechanisms involved in interconversion of CD44 and CD24 phenotypes." (PMID 22693526, 2012). "Cancer stem cells express numerous universal markers such as CD133, CD44, CD24, ESA and ALDH1 in different cancers." (PMID 21521521, 2011). "Among selected genes, CD24, CD44, and CD74 are cell surface adhesion molecules shown to be over expressed in various cancers." (PMID 19602232, 2009). "Around half (55%) of tumors had cancer cells that were double positive for CD44 and CD24." (PMID 40943144, 2025). "Once inside the cancer cells, GATA3 acts as a transcription factor, upregulating CD24 expression." (PMID 40330466, 2025). "CD24 and CD44 surface markers regulate phosphorylation and acetylation of signal transducer and activator of transcription-3 (STAT3), maintaining stemness and EMT of cancer cells." (PMID 39860065, 2025).
cancer (continued). "In recent years, CD24, as a brand-new phagocytic checkpoint, has become a popular potential target for the treatment of cancer and non-neoplastic diseases." (PMID 40486886, 2025). "This overlap suggests that CD24, CD133, and CD326 may share similar self-renewal characteristics, highlighting their potential role in identifying cancer stem-like cells." (PMID 40830621, 2025). "Besides, by evaluating the expression levels of cancer stem cell (CSC) surface markers, EpCAM, CD24, CD133 and CD44 by flow cytometry, we confirmed a direct correlation between stemness markers levels and PHGDH expression in HCT8 and RKO P1 colonspheres." (PMID 40640948, 2025). "It is currently believed that CD24 can alter the expression levels of DNA repair genes (such as L1CAM and NBS1) on the cell membrane by acting as a controller of lipid rafts, to counteract the toxicity and damage to cancer cells induced by cisplatin." (PMID 40486886, 2025). "ARID1B OE significantly increased the number of spheroids and elevated the portion of CD44+/CD24‐ and ALDH‐positive cancer stem cell populations, suggesting that ARID1B plays a critical role in promoting cell survival and the maintenance of cancer stem cells." (PMID 40671262, 2025). "Furthermore, our study demonstrates that circ_0000467 promotes cancer stem cell (CSC) characteristics, as evidenced by increased spheroid formation and elevated levels of CSC markers (CD24, CD44, EpCAM, SOX2, and Nanog)." (PMID 40290725, 2025). "Furthermore, we also observed the downregulation of the mRNA expression of several key cancer stemness markers following CLF treatment, including CD44, CD24, BMI1, and HES1." (PMID 41303378, 2025). "Cancer cells can evade clearance by macrophages through overexpression of antiphagocytic surface proteins including CD47, programmed cell death ligand 1 (PD-L1), the beta-2 microglobulin subunit of the major histocompatibility class I complex (B2M), and CD24." (PMID 38702326, 2024). "Understanding the interplay between CD24 and NKG2D opens new avenues for cancer immunotherapy." (PMID 38881902, 2024). "There are many markers that could differentiate CSCs from NSCs such as CD44, CD133, CD24, EpCam, ALDH1A1, etc.; these markers are highly expressed in wide types of cancer 25-27." (PMID 39513121, 2024). "Western blot was adopted to assess the expression of cancer stem cell markers CD44, CD24 and ALDH1." (PMID 38526702, 2024). "Functional cellular assays demonstrated that IL21-AS1 could protect cancer cells from macrophage-mediated phagocytosis and promote ovarian tumorigenesis via the IL21-AS1–HIF-1α–CD24 and/or IL21-AS1–miR-561-5p–CD24 axes." (PMID 38702326, 2024). "In recent times, the focus on phagocytosis checkpoints, notably CD24, has increased as potential targets for treating cancer and non-neoplastic conditions." (PMID 38881902, 2024). "Likewise, 92% of the Hs-578t cancer cells showed the CD44+/CD24− immunophenotype, whereas the CD24−/CD44−, CD24+/CD44+, and CD44−/CD24+ subpopulations constituted 7.7%, 0.2%, and 0%, respectively." (PMID 38392969, 2024). "Moreover, immunofluorescence (IF) analysis of two cancer nodule sections obtained from patient 1 with BC indicated the presence of CD47 and CD24, which had a broad distribution within the cytoplasm and membrane of malignant cells." (PMID 38971872, 2024). "CD24 and CD44, like discussed previously, are cell surface markers that are often used to identify cancer stem cells, which have the ability to self-renew and differentiate into various types of cancer cells." (PMID 38523788, 2024). "Our findings showed that CoQ0 upregulated CD24 expression and downregulated CD44 expression in a concentration-dependent manner, shifting the CD24/CD44 ratio in favor of suppressing the cancer stem-like properties of OECM-1 and SAS cells under normoxia and hypoxia." (PMID 38904007, 2024).
cancer (continued). "As shown in our data, although overexpression of IL21-AS1 in A2780 and ES2 cells increased the CD24 protein level, it did not alter macrophage-mediated clearance of these cancer cells, similar to the findings in the SKOV3 sublines tested." (PMID 38702326, 2024). "More recent exploration of the cancer engulfment hypothesis has uncovered additional pathways including calreticulin, CD22, and CD24 that intersect with or run parallel to the SIRPα-CD47 pathway and are also potential targets in cancer." (PMID 36459066, 2023). "While preclinical studies exploring CD24 antibody-based therapies have been conducted and reviewed previously, it’s worth noting that as of now, there have been no clinical trials targeting CD24 in cancer treatment." (PMID 38313430, 2023). "Primarily, CD24 as a GPI-anchored protein, is located in the cell membrane in both normal and cancer cells, but is also distributed in the cytoplasm and nucleus in some cancer cells." (PMID 36882399, 2023). "CD24, EPCAM, and CD133, the markers of cancer stem cells (CSCs) reflected the stemness." (PMID 37466793, 2023). "Cancer stem cells are identified and can be isolated based on the expression of specific cell-surface proteins that act as molecular biomarkers, among which the most frequent markers are CD44, CD133, CD24, EpCAM, and LGR5." (PMID 37367867, 2023). "Consequently, we first collected a panel of human MCL cell lines in order to assess CD24 surface expression by flow cytometry, showing heterogenous but higher levels of Median Fluorescence Intensity (MFI) if compared to CD24− cancer cell line." (PMID 37654003, 2023). "The CD24-Siglec 10/G interaction is an innate checkpoint that abrogates inflammatory responses to molecules released by damaged cells, but its role in cancer immunology is not well defined." (PMID 37346042, 2023). "In the present review, we summarize the recent progress and understanding of CD24 and CD200 as emerging immune checkpoint signals in cancer as well as their interaction with their cognate receptors, sialic acid-binding immunoglobulin (Ig)-like lectin 10 (Siglec-10) and CD200 receptor (CD200R)." (PMID 37894750, 2023). "Therefore, it was necessary to block the connection between them using ICIs - CD24 and CD47 antibodies, enabling macrophages to begin phagocytosing cancer cells more effectively." (PMID 37875918, 2023). "Their results showed that the growth of the first two cancer cell lines was strongly inhibited, while the growth of the cell lines with low or no CD24 expression was weakly inhibited or not affected." (PMID 38137380, 2023). "Although CD24 is best known for its involvement in cancer, it also plays a role in various nonneoplastic diseases." (PMID 38313430, 2023). "We then explored by real-time qPCR the impact of miR-662 overexpression in MDA-MB-231 cells on expression levels of well-established stemness markers that are involved in embryogenesis and cancer –NOTCH1, WNT7b, ZEB1, TCF3, CTNNB1, CD44, CD24, SNAI2, OCT-04, c-MYC, EZH2–." (PMID 37443350, 2023). "Besides the proliferative effects, CD24 promotes binding to P-selectin and activates integrins A3B1 and A4B1, thus facilitating cancer cell adhesion to fibronectin, laminin and collagen I and IV." (PMID 37108193, 2023). "For instance, cancer cells are defined as CD31−/CD45-/7-AAD- cells, and CSCs are defined as CD24+/CD133+/epithelial cell adhesion molecule (EpCAM)+ cells after immunofluorescence staining and sorting by flow cytometry in some single-cell analyses of liver cancer." (PMID 35574365, 2022). "We constructed a PPI network via a STRING database to study the interaction between CD24, CD44 as cancer stem cell markers, and vimentin and E-cadherin as epithelial mesenchymal transition markers with a significant expression of the proteomics composition of WHF." (PMID 35735628, 2022).